AAR2 (AAR2 splicing factor)
Description:
Component of the U5 snRNP complex that is required for spliceosome assembly and for pre-mRNA splicing.
Synonyms: C20orf4; CGI-23; bA234K24.2
Tractability: PROTAC: ubiquitination databases record sites on it; its protein half-life has been measured.
Gene: Protein-coding gene on chromosome 20 (36,236,131 to 36,270,918, forward strand). Ensembl gene ENSG00000131043.
Subcellular location (Human Protein Atlas): Cytosol
Gene Ontology:
Molecular function: protein binding
Biological process: negative regulation of mRNA splicing, via spliceosome; spliceosomal snRNP assembly; spliceosomal tri-snRNP complex assembly
Cellular component: U5 snRNP
Genetic constraint (gnomAD): Loss-of-function variants: 31 observed, 28.41 expected, observed/expected ratio (o/e) 1.09, 90% interval 0.82 to 1.47. The upper end of that interval is the gene's LOEUF score, 1.47, which puts it in group 6 of 6, group 1 being the genes least tolerant of losing a copy. Missense variants: 430 observed, 517.67 expected, observed/expected ratio (o/e) 0.83, 90% interval 0.77 to 0.9. Synonymous variants: 188 observed, 206.83 expected, observed/expected ratio (o/e) 0.91, 90% interval 0.81 to 1.03.
Homologues: Orthologues: macaque AAR2 (98% identical), dog AAR2 (94% identical), rabbit AAR2 (93% identical), guinea pig AAR2 (92% identical), pig AAR2 (91% identical), mouse Aar2 (91% identical), rat Aar2 (90% identical), chimpanzee AAR2 (88% identical), zebrafish aar2 (61% identical), tropical clawed frog aar2 (57% identical), Caenorhabditis elegans F10B5.2 (33% identical), Drosophila melanogaster CG12320 (32% identical).
Diseases named in the same sentence as AAR2 in open-access papers:
AAR2 is named in the same sentence as 6 diseases in open-access papers, as found by Europe PMC text mining. Sharing a sentence is not in itself a finding about the gene and the disease. The quoted sentences say what the papers report.
cancer of the brain (1 paper, 2025). "According to the Immune Epitope Database and Analysis Resource (IEDB), PEP3 shares 5 of the 9 amino acids with a peptide that belongs to the AAR2 protein, which is involved in cancer of the brain (glioblastoma) and ankylosing." (PMID 40153397, 2025).
AAR2 also shares sentences with these, for which no sentence is quoted: cancer (1 paper); colorectal adenocarcinoma (1); glioblastoma (1); liver cancer (1); tumor (1).